CD4 (CD4 molecule)
Diseases named in the same sentence as CD4 in open-access papers (continued):
Sharing a sentence is not in itself a finding about the gene and the disease.
tumor (continued). "MCTC-type (tryptase-positive and chymase‐positive) and CD4+ Th2 were shown to express IL-4 in DLBCL and therefore, they may actively promote survival of the tumor cells." (PMID 33343570, 2020). "Meanwhile, PD-1 antibody treatment inhibited the tumor growth, increased the survival time of mice, and resulted in an increased CD45+CD4+ and CD45+CD8+ T cell infiltration or decreased CD11b+Gr1+ myeloid cell infiltration in tumors compared to that in the control group 24." (PMID 32194840, 2020). "Based on the results above that showed differences in secreted cytokines within the tumor between the WT and GCSFR−/− mice, we next asked whether G-CSFR plays a role in the development of CD4+ T cell phenotypes." (PMID 33042110, 2020). "However, in contrast to antigen presentation via MHC class I, prominently via (cancer) epithelial cells, that activate tumor cytotoxic CD8+ T cells, MHCII presentation in the TME usually activates CD4+ Treg that actively suppress cancer immunity." (PMID 32887380, 2020). "Next, we investigated whether ACAA1 expression was correlated to infiltration of immune cell in the tumor microenvironment, including B cells, CD8+ and CD4+ T cells, macrophages, neutrophils, and dendritic cells." (PMID 33194642, 2020). "In practice, others have found that tumor hypoxia upregulates CCL28, a chemokine that recruits CD4+CD25+FOXP3+ Treg cells in an ovarian cancer mouse model, linking it to a more tolerigenic TME and increased tumor vascularization via vascular endothelial growth factor A." (PMID 35310881, 2020). "The results indicated a significant negative correlation between PD-L1 expression and tumor-infiltrating CD4+ T-cells (rs = −0.292, P = 0.02) and CD8+ T-cells (rs = −0.329, P = 0.009)." (PMID 33062072, 2020). "The CD4 naive T cells were excluded, as they were almost absent in both tumor and non-tumor tissues." (PMID 32850758, 2020). "However, the presence of CD4+ and CD8+ T cells in the tumor has been demonstrated to correlate with better prognosis." (PMID 35582441, 2020). "In elderly patients, proliferation and activity of CD4+ and CD8+ T cells and B cells decreased, while those of immunosuppressive cells increased, which formed an immunosuppressive microenvironment that facilitated tumor progression." (PMID 32226776, 2020). "Interestingly, both CD4+ and CD8+ cells from bcl-2 overexpressing tumor produced lower levels of interferon γ (IFNγ) compared with control ones." (PMID 32269145, 2020). "After correcting for gender, race and tumor purity, we identified that B cells, CD8+ T cell, CD4+ T cell, neutrophils, dendritic cells, CCL21, age (P=0), tumor stage (P=0), macrophage infiltration (P=0.035) and CCL8 (P=0.033) were associated with clinical outcomes of BC." (PMID 33146700, 2020). "In this condition, the potential repertoire of tumor antigens that professional APC could process and expose via their MHC-II molecules for CD4+ Th cell scrutiny is relatively limited in both quality and quantity." (PMID 33138029, 2020). "Indeed, CUR significantly increased the number of CD4+ and CD8+ T lymphocytes within the transplanted tumor when administered together with the rV-neuT vaccine." (PMID 32423101, 2020). "First, released DAMPs contributed to the maturation of APCs, enabling APC‐mediated priming or re‐stimulation of T cells locally within the tumor or tumor‐draining LNs after IRE, which was extremely helpful for the increase in effector and memory CD4+ and CD8+ T cells." (PMID 32508058, 2020). "Since thymic epithelial cells induce T-cell differentiation, TET tumors are estimated to form the tumor immune microenvironment of TETs, implying that differences in CD4 and CD8 single-positive T-cell properties are based on differences between B3/C and non-B3/C tumor cells." (PMID 32132638, 2020). "Ectopic expression of ICOS ligand can result in CD8 T-cell co-stimulation and tumor regression in the absence of CD4 T-cells." (PMID 31959281, 2020).
tumor (continued). "When CD4+, in addition to CD8+, cells were depleted, there was no additional effect on the tumor, suggesting CD4+ T cells do not play a significant role." (PMID 32106810, 2020). "Tumor growth, blood lymphocyte levels, cell cycle progression, apoptosis, apoptotic regulator expression, TNF-α expression, changes in mitochondrial membrane potential (MMP), PCNA, and CD4+ and CD8+ T cells in tumor cells were quantitatively evaluated by flow cytometry or RT-PCR." (PMID 32345289, 2020). "However, when assessed by gene expression analyzes, CD3, CD4, and CD56 was significantly upregulated compared to primary tumor (P < .001, <.001, and .002, respectively)." (PMID 32383556, 2020). "From the tumor biopsy taken from a well-responding patient, we found a number of CD4+ T cells secreting granzyme B (GrB), but little to none were found in the biopsy obtained from the non-responder." (PMID 32036449, 2020). "We explored whether and to what extent both CD8+ and CD4+ T cells are involved in the therapeutic effects of anti-neu mAb in both WT BALB/c and BALB/c-NeuT tumor bearing mice." (PMID 32127568, 2020). "Heat treatment by magnetite cationic liposomes in murine glioma subcutaneous flank tumor models resulted in resolution of the treated tumor as well as an untreated tumor on the opposite side, with increased CD8+ and CD4+ T cell tumor activity and infiltration at both locations." (PMID 32672126, 2020). "Although T cell infiltration in ICB NR tumors was significantly lower compared to ICB R tumors, no alterations in relative frequencies of CD8+ and CD4+ tumor-infiltrating lymphocytes (TILs) of ICB R compared to NR mice were observed." (PMID 32071302, 2020). "Furthermore, both CD4+ and CD8+ PD-L1-CAR T cells exhibited efficient cytotoxicity against PD-L1high tumor cells." (PMID 32792499, 2020). "In a first series of experiments, it was found that the in vivo depletion of CD4+ T cells in CIITA-tumor vaccinated and protected mice did not dramatically alter the capacity of vaccinated mice to respond and reject parental-tumor cells." (PMID 33138029, 2020). "Strikingly, no strong correlation between the proportion of CD8+ and CD4+ tumor-reactive TILs was detected, suggesting the accumulation of these responses in the tumor microenvironment to follow non-overlapping biological pathways." (PMID 33198174, 2020). "The CD4/CD8 ratio in PB has been reported to decrease during disease progression, and has been considered as an independent unfavorable marker related to advanced disease and increased tumor burden." (PMID 33158030, 2020). "So, the combination therapy of ipilimumab and nivolumab targeting both CD4 + PD-1lowTIM-3+ and CD8+ PD-1highTIM-3+ might be able to reverse the natural prognosis of RCC and be ideal for treating patients with higher tumour grade." (PMID 32277125, 2020). "Hence, both B16 and MC38 tumor harbored phenotypically suppressive Tregs, exhausted CD8+PD1+TIM3+ TILs and PD1-expressing conventional CD4+ TILs." (PMID 32690667, 2020). "Indeed, low-dose CUR increased the frequency of CD4+ and CD8+ T lymphocytes in the spleens of immunocompetent tumor-bearing mice." (PMID 32423101, 2020). "In preclinical studies, C-REV replicated effectively within tumors and induced an antitumor immune response, as evidenced by an increase in the numbers of activated CD4+, CD8+ T, and NK cells in tumor tissues, leading to prolonged survival and a significant reduction in tumor growth." (PMID 33207653, 2020). "Disruption of EZH2 activity in Tregs, either pharmacologically or genetically, drove the acquisition of pro-inflammatory functions in tumor-infiltrating Tregs, remodeling the tumor microenvironment and enhancing the recruitment and function of CD8+ and CD4+ effector T cells that eliminate tumors." (PMID 32723346, 2020).
tumor (continued). "Further exploration of the interaction between CD4+FOXP3+ T cells and CD8+ T cells may improve our understanding of tumor‐specific T‐cell activity in the tumor microenvironment, with potential impact on the development of immune‐modulatory therapies." (PMID 32377339, 2020). "Combining an approach that would elicit potent CD4+ and CD8+ T cell responses may result in more durable anti-tumor responses." (PMID 33298945, 2020). "CD4+ T cells, CD8+ T cells, and IFN-γ play critical roles in conferring the anti-tumor effects." (PMID 33015115, 2020). "A comprehensive analysis of cytokine profiles activated by IL-33 in various cancers may help clarify the CD4+ T cell subsets (including Treg) targeted by IL-33 in relation to the specific TME and anti-tumor response elicited." (PMID 33329534, 2020). "Likewise, the proportions of lymphocytes, B cells, total T cells, CD3+CD4+ T cells, natural killer T cells, and CD3+CD8+ T cells in the spleen and tumor tissues of the JK5G group were observably upregulated compared to those in the model group (all p < 0.05)." (PMID 33178591, 2020). "Infiltrating CD4+ and CD8+ Te or Tem subsets might facilitate the establishment of local tumor dormancy as well as distant tumor dormancy because naïve FVBN202 transgenic mice as well as FVB mice without tumor dormancy lacked predominant Te subset." (PMID 33115528, 2020). "Additionally, CD8+ and CD4+ T cells, two subpopulations of CD3+ T cells, play different roles in tumor immune responses." (PMID 32927747, 2020). "Depletion of CD8+ T cells abrogated the therapeutic efficacy of IR, but not depletion of CD4+ T cells or macrophages highlighting the critical requirement for CD8+ T cells in facilitating radiation-induced tumor control." (PMID 33238631, 2020). "Contrastingly, TH2-polarized CD4+ T cells and other TH2 response-initiating cells, such as TH2-polarized monocytes and macrophages, and regulatory B cells (Bregs), are crucial pro-tumorigenic components that promote tumor cell survival and proliferation." (PMID 32083005, 2020). "Thus, we further focused the functional phenotype for CD4+ and CD8+ T cell immune responses between the two groups (PBS-administered and Ocs-P-administered tumor-bearing group)." (PMID 33105813, 2020). "The result demonstrated that the expression of 8 hub genes have negative correlation with tumor purity and their expression level were positively correlated with the infiltration of CD4 T cells, macrophages, neutrophils and dendritic cells." (PMID 32859214, 2020). "In experiment 2 there was a significant correlation seen at 7 days after oHSV treatment between reduced tumor volumes and increased intratumoral numbers of GP33+ CD8+ T cells (p = 0.007), gB498+ CD8+ T cells (p = 0.007), CD4+ T cells (p = 0.032), as well as reduced numbers of M-MDSCs (p = 0.015)." (PMID 32198420, 2020). "Tumor-infiltrating CD4+ and CD8+ T-cells, Treg cells, as well as innate immune cells, such as dendritic cells, macrophages, and NK cells, are all involved in “immunoediting”, finally leading to an immune escape of the tumor." (PMID 32466578, 2020). "If either TNFα or IFNγ signaling in tumor-infiltrating CD4+ T cells is absent upon antigen recognition, tumor progression is stimulated, whereas combined TNFα and IFNγ signaling in CD4+ T cells prevents tumor angiogenesis and tumor-cell proliferation." (PMID 32733461, 2020). "However, a small fraction of both CD4+ and CD8+ T cell subsets recruited to the tumor microenvironment had a reduced level of CD5." (PMID 33584650, 2020). "An increased ratio of M1-type macrophages to M2-type macrophages, and the CD3+CD4+ T cells and CD3+CD8+ T cell quantities in tumor tissues after treatment with M1/SLNP indicated M1/SLNP could relieve the immunosuppressive tumor microenvironments." (PMID 34138195, 2020). "The immunoselection of tumor variants lacking strong tumor-specific antigens by CD8+ and CD4+ T cells represents another mechanism by which cancer cells escape tumor immunity." (PMID 31936322, 2020).
tumor (continued). "In addition, we also found the subtypes of T cells (CD4 and CD8) were enriched in TILs compared to tumor samples." (PMID 32244522, 2020). "Furthermore, we correlated galectin-9 expression on blood CD4+, CD8+, and γδ T cells with tumor size, lymph node metastasis, and UICC stage." (PMID 32055023, 2020). "There were significant changes in tumor infiltrating immune populations in animals treated with 2 g/kg of lactate, namely, increases in the frequency of total (CD3+) T cells, including both CD4+ and CD8+ T cells." (PMID 33095157, 2020). "Circulating leukocytes isolated from naïve mice and tumor-bearing mice at day 7 post tumor inoculation did not exhibit detectable suppressive activity against the proliferation of naive CD4 T cells." (PMID 32770025, 2020). "Tumour- and immune cell-derived EV have been shown to carry tumour antigens, which may primarily act to eradicate established tumours by CD8 + T cells and CD4 + T cells." (PMID 32942702, 2020). "We observed an increasing number of CD4+FOXP3+ T cells in the tumor do not correlate with a reduced MIN distance between CD4+FOXP3+ T cells and tumor cells (r = −0.01, P = 0.95)." (PMID 32377339, 2020). "In addition, CD8+ T cells, CD4+FOXP3+ T cells and DNT cells showed a significant difference in the immune cell: tumor cell ratio between the tumor core and edge." (PMID 32377339, 2020). "Furthermore, we detected an increased frequency of CD4+ T cells producing granzyme B indicating their cytotoxic activity (CTL), possibly as a result of chronic exposure to the tumor." (PMID 32370785, 2020). "Our data indicate that both BH3 mimetics, when simultaneously combined with CAR-T cells, not only impaired the repetitive tumor killing potential of CAR-T cells and the long-term cytotoxicity, but also hampered the early proliferation of both CD4+ and CD8+ CAR-T cells." (PMID 33362794, 2020). "This 'licenses' DCs to present tumor antigens to naïve CD4+ T cells, or cross‐present to naïve CD8+ T cells, triggering cytokine and chemokine release plus activation and infiltration of tumor‐specific T cells to the tumor bed to target cancer cells." (PMID 32994997, 2020). "Because loss of Raptor/mTORC1 increased proinflammatory CD8+IFN-γ+ T cells and CD4+IFN-γ+ T helper cells in LLC tumors, we next determined whether T lymphocytes contribute to tumor suppression seen in RaptorECKO mice." (PMID 32759497, 2020). "Another group indicated on NSCLC TMA samples that a high number of stromal CD4+ and epithelial and stromal CD8+ cells were independent positive prognostic markers, and CD8+ tumor‐infiltrating lymphocytes (TILs) can stratify immunotherapy‐treated patients of different clinical outcome." (PMID 32506804, 2020). "High levels of stromal CD4+ and CD20+ cells associated with improved survival in hormone receptor negative cases (p < 0.04), while tumour nest CD8+ and FoxP3+ cells associated with poor survival in hormone receptor positives (p < 0.005)." (PMID 32577938, 2020). "To investigate how nivolumab influenced PB lymphocyte sub-populations and tumor burden, we determined the counts/ml of CD45+ leukocytes, CD4+ SS cells, and total CD4+ and CD8+ T cells at T0 and after selected nivolumab administrations up to 42 weeks (T42) from the start of therapy." (PMID 33072126, 2020). "Within the tumour‐infiltrating lymphocytes, Tregs are the most numerous population and can suppress T helper cell and CTL responses, while CD8+ and CD4+ T cells are exhausted." (PMID 32567735, 2020). "Moreover, B cells, macrophages, and dendritic cells (DCs) transmitted the foreign peptide antigen to CD4+ T cells through MHC-II on the cell surface, thereby promoting tumor antigen recognition." (PMID 33330629, 2020). "The downstream effects of direct recognition of tumor-antigens by tumor-reactive CD4+ TILs have not been well documented so far." (PMID 33198174, 2020).
tumor (continued). "However, they suggest careful evaluation of therapeutic CD4+ T cell products, in regard to donor-dependent variations, as well as TCR affinity and functional avidity testing, in order to avoid possible tumor growth promoting effects." (PMID 32610710, 2020). "Activated CD4+ effector T cells and Tregs were reported to support EMT of (pre-)malignant pancreatic cells upon the secretion of IL-6 and tumor necrosis factor (TNF) α in vitro, indicating the tumor-promoting role of CD4+ T cells." (PMID 32397303, 2020). "Ablative radiation significantly increased infiltration of CD8+ cells expressing IFNγ (CD8+ effector T-cell) and CD4+ CD25+ FOXP3+ (Treg) cells to the tumor while hypofraction and conventional RT did not." (PMID 32287292, 2020). "In other cases, combined CD8+T cells and cytokine therapy is not enough to eliminate the tumor and introducing CD4+T cells is necessary." (PMID 32148558, 2020). "T cell frequency remained unchanged, but two-way ANOVA revealed that tumor growth significantly decreased the frequency of the subpopulation of T helper cells (CD4+/CD8−; p ≤ 0.05) and increased the frequency of cytotoxic T cells (CD4−/CD8+; p ≤ 0.05) most pronounced in the DIO/Tumor group." (PMID 33244094, 2020). "Having shown that AdIL-17A transduction in 4T1 cells induces both immune activation and MDSC-mediated immune suppression, we hypothesized that IL-17A-activated CD4 and CD8 T cells would exert anti-tumor effects if MDSCs were depleted." (PMID 32770025, 2020). "Additionally, TAMs secrete cytokines such as IL‐10 and transforming growth factor‐β (TGF‐β) to inhibit the activity of CD4+ T cells and CD8+ T cells and mediate the proliferation of Treg cells, and finally maintain the tumor immunosuppressive microenvironment." (PMID 34766109, 2020). "CD4+ T cells can secrete interferon (IFN)‐γ, activate other lymphocyte subsets by releasing T‐cell cytokines, and suppress tumor development by directly killing tumor cells expressing adequate levels of MHC class II molecules." (PMID 32459060, 2020). "In contrast, NKTR-214 drastically reduced the proliferation and enhanced the apoptosis of CD4+ Tregs in tumor tissue, but not in spleen." (PMID 32005826, 2020). "Nonetheless, CD4+CD25+FOXP3+ T cells remains the central focus of Treg-based research in cancer biology due to their potent immunosuppressive functions and their presence in a wide range of tumor types." (PMID 33013886, 2020). "Examination of tumors treated with VG161 compared to equivalent tumors exposed to VG160 provides compelling evidence that VG161 induced a potent systemic anti-tumor immune response in vivo, revealing increased infiltration of NK cells, macrophages, and both CD4+ and CD8+ tumor-specific T cells." (PMID 33182232, 2020). "For example, when combined with poly(I:C) and other adjuvants, Clec9a-fused antigens induce CD4- and CD8-mediated anti-tumor immunity, while fusion of human IFNα to Cle9a led to an anti-tumor response that was improved by treatment with checkpoint blockade in the murine 4T1 mammary tumor model." (PMID 32508825, 2020). "Notably, they found that CD4+ T cells especially Th1-polaralized effector cells and Tregs were major T cell subsets in the TME and that MHC-I expression was frequently lost in tumor cells." (PMID 32787882, 2020). "This may suggest that different tumor and/or microenvironment characteristics and different interactions between immune cells such as CD4+ and CD3+/CD62L+ cells and tumor cells already exist at the beginning of the disease." (PMID 32306920, 2020). "As changes in the CD4+ Th-skewing could affect CD8+ T cell functionality, which is pivotal for effective anti-tumor efficacy, we analyzed the effect of AKT-inhibition on CD8+ T cell functionality in presence and absence of CD4+ T cells." (PMID 32504246, 2020).